CFHR4 (complement factor H related 4)
Description:
Involved in complement regulation. Can associate with lipoproteins and may play a role in lipid metabolism.
Synonyms: FHR-4; CFHL4; FHR4
Tractability: Antibody: its Gene Ontology location is reachable by antibodies, with high confidence; UniProt places it where antibodies can reach, with medium confidence; UniProt predicts a signal peptide or a membrane-spanning region.
Safety:
Unwanted effects reported when the protein is acted on. In parentheses: how it was acted on, where the effect was seen, and who reports it.
maculopapular exanthema (source: ClinPGx)
Gene: Protein-coding gene on chromosome 1 (196,888,014 to 196,920,294, forward strand). Ensembl gene ENSG00000134365.
Subcellular location: Secreted
Pathways (Reactome):
Immune System: Regulation of Complement cascade
Gene Ontology:
Molecular function: complement component C3b binding; lipid transporter activity
Biological process: complement activation
Cellular component: extracellular region
Genetic constraint (gnomAD): Loss-of-function variants: 58 observed, 59.94 expected, observed/expected ratio (o/e) 0.97, 90% interval 0.78 to 1.2. The upper end of that interval is the gene's LOEUF score, 1.2, which puts it in group 5 of 6, group 1 being the genes least tolerant of losing a copy. Missense variants: 579 observed, 618.74 expected, observed/expected ratio (o/e) 0.94, 90% interval 0.87 to 1. Synonymous variants: 225 observed, 215.76 expected, observed/expected ratio (o/e) 1.04, 90% interval 0.94 to 1.16.
Homologues: Orthologues: chimpanzee CFHR4 (47% identical). Paralogues in human: CFHR3 (41% identical), CFH (34% identical), CFHR5 (30% identical), CFHR2 (18% identical), CFHR1 (17% identical), F13B (15% identical), CSMD1 (12% identical), PAPPA2 (12% identical), SVEP1 (12% identical), CSMD3 (12% identical), PAPPA (12% identical), CSMD2 (11% identical), and 27 more.
Diseases named in the same sentence as CFHR4 in open-access papers:
CFHR4 is named in the same sentence as 23 diseases in open-access papers, as found by Europe PMC text mining. Sharing a sentence is not in itself a finding about the gene and the disease. The quoted sentences say what the papers report.
age-related macular degeneration (5 papers, 2021 to 2024). Age-related loss of vision in the central portion of the retina (macula), secondary to retinal degeneration. "Genetic variations in CFHR4 gene have been linked to age-related macular degeneration, systemic lupus erythematosus, and atypical hemolytic uremic syndrome." (PMID 35590261, 2022). "To date, numerous studies have suggested a role for CFHR4 in immune system disorders, such as age-related macular degeneration (AMD), systemic lupus erythematosus and atypical hemolytic uremic syndrome (AHUS)." (PMID 35812416, 2022). "For instance, the absence of CFHR4 increases the risk of the atypical hemolytic uremic syndrome, and the increase of circulation level of CFHR4 was strongly associated with age-related macular degeneration (AMD)." (PMID 36338737, 2022). "Finally, the phenotype scanning uncovered connections between CFH (rs2274700) and age-related macular degeneration (AMD), lung function, B3GNT8 (rs284663) and height, coronary artery illness, basal metabolic rate, as well as CFHR4 (rs4915559) with neovascularization and AMD." (PMID 38778174, 2024).
atypical hemolytic-uremic syndrome (4 papers, 2011 to 2022). A rare, genetic thrombotic microangiopathy due to dysregulation of the alternative complement pathway and characterized by the triad of hemolytic anemia, thrombocytopenia, and acute renal dysfunction. "The combined deletion of CFHR1 and CFHR4 has only been described as an increased risk for the atypical hemolytic uremic syndrome." (PMID 21850184, 2011).
systemic lupus erythematosus (4 papers, 2022 to 2023). An autoimmune multi-organ disease typically associated with vasculopathy and autoantibody production. "Deletion of CFHR4 may limit the ability of C protein to inhibit inflammation, thus promoting the development of systemic lupus erythematosus (SLE)." (PMID 36338737, 2022).
hepatocellular carcinoma (3 papers, 2022 to 2024). A malignant tumor that arises from hepatocytes. "However, the prognostic value of CFHR4 in hepatocellular carcinoma (HCC) is unknown." (PMID 35812416, 2022).
diabetes (2 papers, 2023 to 2025). "As an exemplar of use as a non-invasive diagnostic, logistic regression establishes a composite model comprising four proteins (ADAMTSL2, AKR1B10, CFHR4 and TREM2), body mass index and type 2 diabetes mellitus status, to identify at-risk steatohepatitis." (PMID 37037945, 2023). "Following adjustment for age, sex, BMI, alcohol consumption status, vascular/heart diseases, diabetes, medications for cholesterol, blood pressure, or diabetes, and exogenous hormone use, CD55, CFHR4, and CFHR5 were found to exhibit significant associations with AMD." (PMID 40735363, 2025).
lung carcinoma (2 papers, 2022 to 2023). "For example, lung cancer-specific surface markers, such as Complement factor H-related protein 4 (CFHR4) and Coagulation factor XIII A chain (F13A1)." (PMID 38052753, 2023). "The significant downregulation of coagulation factor XIII A chain (F13A1) and upregulation of the complement factor H-related protein 4 (CFHR4) in SCLC compared to HCs has not yet been identified in other cancers, including lung cancer." (PMID 34996345, 2022).
congenital malformations (1 paper, 2022). "In-depth exploration on the relationship between congenital malformations and changes in maternal plasma CFHR4 or other related proteins at different stages of pregnancy will help to understand the role of these molecules in fetal heart development and CHDs." (PMID 35590261, 2022).
macular degeneration (1 paper, 2016). Loss of vision in the central portion of the retina (macula), secondary to retinal degeneration. "Interestingly, seven genes associated with macular degeneration (CFH, C3, C2, CFHR5, CFB and CFHR4, CFHR1) also form a statistically significant module in liver (p value < 10−26, z score = 10.85)." (PMID 27748412, 2016).
tumor (12 papers, 2017 to 2025). "A univariate Cox regression analysis was performed with TNM stage, pathological grade, tumor status and CFHR4 expression levels to further identify factors associated with different prognoses." (PMID 35812416, 2022). "Moreover, a higher histological grade, TNM grade, pathological stage and tumor status were also significantly associated with low CFHR4 expression." (PMID 35812416, 2022). "As CFHR4 localizes to necrotic tumor tissues and binds necrotic cells, CRP-CFHR4 binding is implicated in the opsonization of necrotic cells." (PMID 37781355, 2023). "Based on these results, patients with HCC presenting lower CFHR4 expression seemed to have a more advanced tumor stage." (PMID 35812416, 2022). "CFHR4, a soluble regulator of the complement cascade, is generally known to boost complement activation, a process presumed to contribute to tumor growth." (PMID 34996345, 2022). "It was found that CFHR4 competed and deregulated FH on the surface of tumor cells, which efficiently led to the macrophages phagocytosis through CDC attack." (PMID 36338737, 2022). "This work contributes to a better understanding of the possible role and prognostic significance of CFHR4 in tumor immunology." (PMID 36338737, 2022). "One supportive evidence is CFHR3, a similar variant of CFHR4 with overlapping functions, was reported highly expressed at the normal liver tissue, while the HCC tumor expressed CFHR3 in significantly lower level." (PMID 36338737, 2022). "More importantly, CFHR4 expression was associated with multiple immune cells and may affect HCC tumor immunity by inducing M1 macrophage polarization and altering the infiltration of exhausted T cells." (PMID 35812416, 2022). "The correlations between CFHR4 and prognosis and tumor-infiltrating lymphocytes in HCC are yet unknown." (PMID 36338737, 2022). "Therefore, it is reasonable to speculate that the over-expression of CFHR4 within the tumor might allow the complement system to reverse the immune suppressive phenotype cause by the FH, thus overcome the immune escape ultimately." (PMID 36338737, 2022). "The down-regulation of CFHR4 in HCC cells might facilitate the tumor progression and malignancy." (PMID 36338737, 2022). "This yielded 88 genes associated with tumor grade, in which seven DEGs (C8orf33, TSNAXIP1, TM4SF1, CTH, ANXA2, KIAA1522 and LRRC1) can distinguish HCC of G3 from G1, two DEGs (CYB5A and RRAGD) can distinguish HCC of G3 from G2, and two DEGs (CFHR4 and F13B) can distinguish HCC of G3 from G4." (PMID 29123978, 2017). "The analysis of TCGA data showed that, CFHR4, DNASE1L3, and SPP2 were significantly higher in adjacent non-tumor tissues, while TAF6 was upregulated in HCC tissues." (PMID 36248822, 2022). "We explored the relationship between CFHR4 expression with OS, PFI, DSS and clinical characteristics (TNM stage, residual tumor, and histological grade) by performing univariate Cox regression analysis." (PMID 35812416, 2022). "Low CFHR4 expression in HCC tissues was significantly correlated with the patients’ sex, race, age, TNM stage, pathological stage, tumor status, residual tumor, histologic grade and alpha fetal protein (AFP) level." (PMID 35812416, 2022). "We also identified 44 lost segments, which harbored tumor suppressors including CDKN2A (9p21.3), ADAM3A (8p11.22), and CFHR1/CFHR4 (1q31.3)." (PMID 34070941, 2021). "We speculate that the expression of CFHR4 in HCC may be an important mediator for the development of TME, which involves in the tumor immune evasion." (PMID 36338737, 2022). "Importantly, CFHR4, which was screened from DEGs, was shown to express at a lower level in HCC tumor tissue than normal tissues." (PMID 36338737, 2022). "Secondly, However, the potential diagnostic value of the circulating CFHR4 content in HCC patients is not clear, and the clinical significance of circulating tumor markers remains to be further explored." (PMID 35812416, 2022).
tumor (continued). "Decreased CFHR4 in HCC might be relevant with resistance of tumor cells against the mechanism of CFHR4-enhanced complement attack as mentioned, leading to the disordered immune regulation and tumor survival from the complement-mediated attack." (PMID 36338737, 2022). "Subsequently, according to the expression level of CFHR4, HCC samples were dichotomized into CFHR4-high and low expression groups, we aimed to reveal whether different expression groups of CFHR4 differ in the tumor immune microenvironment of HCC." (PMID 35812416, 2022). "The real-time quantitative PCR results showed that CFHR4, SPP2, and DNASE1L3 were expressed higher in non-tumor tissues (Non-Tumor) than in tumor tissues (Tumor), and TAF6 was expressed higher in tumor tissues than in non-tumor tissues." (PMID 36248822, 2022).
cancer (5 papers, 2019 to 2022). A tumor composed of atypical neoplastic, often pleomorphic cells that invade other tissues. "CFHR4 mRNA levels were inversely correlated with a cancer family history, histological grade, TNM stage, and serum AFP level of HCC patients." (PMID 36338737, 2022). "CFHR4 (fold change of 8.4) had higher levels in samples from patients with cancer in the right colon compared to the rectum." (PMID 32452655, 2020). "In samples from patients with stage III cancer, levels of CFHR4 were over 40 times higher in samples from patients with cancer in the right colon." (PMID 32452655, 2020). "The top three proteins, KRT16 (with a fold change of 45.6), CFHR4 (with a fold change of 41.2), and CFHR1 (with a fold change of 27.9), all displayed higher plasma levels in samples from patients with stage III cancer in the right colon than the rectum." (PMID 32452655, 2020). "Levels of keratins, type I cytoskeletal 16 (KRT16), 9 (KRT9), and 10 (KRT10), as well as complement factor H‐related protein 4 (CFHR4) and 1 (CFHR1), had higher levels in plasma samples from patients with cancer in the right colon (with fold changes between 6.2‐13.0)." (PMID 32452655, 2020). "However, few studies on CFHR4 have been conducted, and no studies have determined its role in cancer." (PMID 35812416, 2022).
CFHR4 also shares sentences with these, for which no sentence is quoted: acute pancreatitis (1 paper); breast tumour (1); COVID-19 (1); geographic atrophy (1); heart diseases (1); immune system disorder (1); lymphoma (1); pertussis (1); primary hyperoxaluria (1); retinal disease (1); staphylococcus aureus infection (1); type 2 diabetes mellitus (1); ventricular septal defect (1).